IL12B (interleukin 12B)
Diseases named in the same sentence as IL12B in open-access papers (continued):
Sharing a sentence is not in itself a finding about the gene and the disease.
Crohn disease (17 papers, 2009 to 2026). A gastrointestinal disorder characterized by chronic inflammation involving all layers of the intestinal wall, noncaseating granulomas affecting the intestinal wall and regional lymph nodes, and transmural fibrosis. "Variation in the IL12B gene has been linked strongly to the pathogenesis of Crohn’s disease and an antibody targeted towards the p40 subunit of IL12 demonstrated efficacy in the treatment of moderate-to-severe Crohn’s disease." (PMID 32641083, 2020). "IL12B has been associated with Crohn's disease in three independent GWAS as well as subsequent candidate gene studies." (PMID 25473852, 2014). "We analyzed IL12B gene variants regarding association with Crohn's disease (CD) and ulcerative colitis (UC)." (PMID 22479607, 2012). "IL12B levels were associated with Crohn’s disease (beta 0.42, se 0.05, P 2.76 × 10−15)." (PMID 32641083, 2020). "Genome-wide association studies have revealed that IL23R and five additional genes involved in Th17 differentiation (IL12B, JAK2, STAT3, CCR6 and TNFSF15) are associated with susceptibility to Crohn’s disease." (PMID 36498596, 2022). "We demonstrated putative causal relationships between CD6 and IL18R1 with inflammatory bowel disease and between IL12B and Crohn’s disease." (PMID 32641083, 2020). "Analysis for gene-gene interaction of IL12B with IL23R and STAT4 variants, respectively, regarding susceptibility to Crohn's disease (CD)." (PMID 22479607, 2012). "This study confirms the very strong involvement of IL-23R and, to a lesser extent, IL-12B, in Crohn's disease in New Zealand." (PMID 21253534, 2010). "We tested whether genes associated with Crohn's disease are also associated with ankylosing spondylitis and confirmed that the two diseases share associations at chromosome 1q32 near KIF21B, STAT3, IL12B, CDKAL1, LRRK2/MUC19, and chromosome 13q14." (PMID 21152001, 2010). "This study of genes associated with Crohn's disease has identified definite genome-wide significant association with AS of SNPs at chromosome 1q32 near KIF21B, and experiment-wise association at five other novel-AS loci including STAT3, IL12B, CDKAL1, LRRK2/MUC19, and at chr13q14." (PMID 21152001, 2010). "These pathways involve key cytokines and signal transducers, such as IL-23R, IL-12B, IL-21, IL-4, and IL-5, in psoriatic arthritis; IL-23R, IL-12B, IL-13, Rel, TYK2, and JAK2 in Crohn's disease." (PMID 32161545, 2020).
COVID-19 (15 papers, 2020 to 2025). A disease caused by infection with severe acute respiratory syndrome coronavirus 2. "It has been hypothesized that death from COVID-19 may be associated with immunogenetic markers including IL12B, along with HLA-B, IL6, and IL10." (PMID 36800980, 2023). "We consecutively included patients during the first peak of the COVID-19 epidemic in Brazil and analyzed the expressions of genes encoding interleukin (IL)-1β, IL-6, IL-8, IL-10, IL-12A, IL-12B, and tumor necrosis factor-α in peripheral blood mononuclear cells." (PMID 33819170, 2021). "In particular, we observed increase inthe levels of cytokines known to contribute to cytokine storms as IL-1β, IL-6, IL-12A, IL-12B, IFN-γ, and TNF-α as well as various chemokines and CSFs upon infection with the COVID-19 variants." (PMID 39759510, 2024). "Among the gene profiles demonstrated in this study, the SNPs of NLRP3 and IL12B were consistently defined as potential factors for specific antibody production and maintenance after COVID-19 vaccination." (PMID 37564647, 2023). "The proinflammatory cytokines TNF-α, IL-1β, IL-8, IL-6, and IL12-B (P < 0.05) were increased in patients who had contracted COVID-19." (PMID 33819170, 2021). "These migratory DCs express IL10 in health, but TNF and the common IL-12 and IL-23 subunit IL12B in COVID-19, suggesting altered capacity for T cell polarization." (PMID 33879890, 2021). "suggest that IL6 and IL12B play a role in the development of COVID-19." (PMID 36157452, 2022). "Our in-depth phenograph-guided analysis of the neutrophil compartment revealed the enrichment of activated neutrophil immunotypes in moderate COVID-19 patients, associated with higher circulating levels of molecules involved in the IFN-mediated antiviral response (i.e., IRF9, IL-12b, IFNɣ)." (PMID 34548411, 2021). "Specifically, we found that the expression of genes encoding proinflammatory cytokines (IL12B, IL15, IL6, IL12A and IL1B) and chemokines (CXCL9, CXCL11 and CXCL10) was broadly increased in COVID-19 patients and speculate that other viral infections may also induce expression of these genes." (PMID 33780352, 2021). "Through the analysis of the propensity score-matched biomarker screening cohort, we identified Flt3L, TRAIL, CXCL5, IL-12B, MCP-3, IL-24, and IL-8 as candidate biomarkers for severe progression of COVID-19 in elderly patients." (PMID 40426989, 2025). "The key targets of Paxlovid against LUAD/COVID-19 were obtained through network pharmacology, the most important targets include IL6, IL12B, LBP." (PMID 36157452, 2022). "Our multivariate model showed that COVID-19 was related to increased expression levels of TNF-α, IL-1β, IL-6, IL-8, IL-12B, and IL-10 (P < 0.05), and that leprosy simultaneously enhanced the levels of IL-6 (P = 0.046) and IL-12B (P = 0.020)." (PMID 33819170, 2021). "Conversely, serum levels of IFNG and IL12B were significantly lower in severe COVID-19 among SOT recipients, but not among controls." (PMID 39794319, 2025). "Among them, several of the classical inflammatory markers, e.g., IL6, IL8, IL10, IL12B, TNF, and IFNγ had substantially higher levels in sepsis compared to COVID-19, leading to the conclusion that the inflammatory response is more pronounced in sepsis regardless of etiology or focus of infection." (PMID 36829233, 2023). "Subsequently, Paxlovid was analyzed against the core targets of LUAD/COVID-19 (CXCL2, CCL2, IL12B, CSF3, LBP, IL6, CXCL10) and Paxlovid, and the results showed that IL-6, IL12B, LBP and Paxlovid could be combined." (PMID 36157452, 2022). "Among others, cytokine-related genes IL12B and TNFSF10 and members of the Krüppel-like factors (KLF) and CCAAT/enhancer-binding protein (CEBP) family of transcription factors as well as transcription factor 7 (TCF7) were affected only in COVID-19-derived PBMCs." (PMID 37614228, 2023).
inflammatory bowel disease (15 papers, 2012 to 2025). A spectrum of small and large bowel inflammatory diseases of unknown etiology. "Recent genome-wide association studies (GWAS) identified that IL-12B and IL-23R are susceptibility genes for inflammatory bowel disease (IBD)." (PMID 36430241, 2022). "Recent genome-wide association studies identified IL12B and IL23R as susceptibility genes for inflammatory bowel disease (IBD)." (PMID 22479607, 2012). "Consistent with this, genetically instrumented higher interleukin-12 subunit beta (encoded by IL12B) was associated with a higher risk of CD (OR 2.02; 95% CI 1.48, 2.76), UC (OR 1.56; 95% CI, 1.31, 1.87), and inflammatory bowel disease (IBD) (OR 1.56 95%CI 1.31, 1.87)." (PMID 32591531, 2020). "The role of IL-12 and IL-23 signaling in the development of IBD is highlighted by the fact that patients with complete loss-of-function mutations in IL23R, IL12RB1, or IL12B do not develop spontaneous inflammatory bowel disease." (PMID 39795980, 2024).
colitis (13 papers, 2012 to 2025). Inflammation of the colon. "Mef2c promoted M1 macrophage polarization by directly activating the transcription of Il2a and Il12b, facilitating resistance to Listeria monocytogenes infection and susceptibility to colitis." (PMID 37733446, 2023). "SF68 did not cause pathological inflammation and increases of colonic cytokine expression, whereas UC-derived strain IB44a caused pathological colitis and increased expression of Tnf, Il12b, and Il17a." (PMID 31767028, 2019). "Colitis in Cdcs1+/+Il10ra−/− mice is characterized by marked elevation of inflammatory cytokines, including Il12b, Infg, Il1b and Tnf17." (PMID 35013585, 2022). "Genetic deletion of Il12b in E4BP4 knockout mice completely prevents the development of colitis." (PMID 40332348, 2025). "Our results indicated that the absence of myeloid STING significantly decreased the levels of Il12b, Il12a, and Il23a in colitis and the deletion of STING in DMXAA-treated BMDMs/BMDCs noticeably suppressed pathways related to the IL-12 family and IL-12/IL-23 production." (PMID 39113810, 2024). "In this work, we showed that the induction of colitis by DSS administration caused a clear pro-inflammatory response (increase of COX-2, TNF-α, IL-12b, and IL-23 mRNAs) in the colon, which was significantly down-regulated after the administration of 5-ASA plus berberine." (PMID 26642326, 2015). "We examined the effects of 11R-VIVIT administration on the course of colitis in piroxicam treated Il10−/− mice, a commonly used murine IBD model characterized by increased colonic Il12b expression." (PMID 22479554, 2012). "Dissimilarly, rCsCP ameliorated colitis mainly through stimulating innate immunity, such as Toll like receptor (TLR) signaling pathway, down-regulating the expression of inflammatory cytokines (e.g., IL-12b, IL-23r and IL-7), thereby restraining the differentiation of Th1/Th17 cells." (PMID 36084127, 2022). "It is noteworthy that LPS-induced production of IL-12a, IL-12b, IL-23a, and IL-6 mRNA was not suppressed in colon CD11c+ DCs from Wnt5aMxΔ/Δ mice, which are consistent with the observation that Wnt5aMxΔ/Δ mice showed the phenotypes similar to control mice in DSS-induced colitis." (PMID 26030277, 2015).
leprosy (10 papers, 2013 to 2025). Leprosy is a chronic infectious disease affecting primarily the skin and peripheral nervous system. "In Indian patients, subjects with leprosy were less likely to have the 3′UTR genotype associated with lower IL-12B expression." (PMID 26793196, 2015). "In addition to the HLA locus, we were able to consistently replicate the LACC1 and IL12B loci previously associated with leprosy in the Chinese population both in the discovery GWAS and the replication sample." (PMID 32421744, 2020). "We also validated two previously identified risk factors for leprosy, a missense variant in the LACC1 gene, and an intergenic variant located close to the IL12B gene." (PMID 32421744, 2020). "Two IL-23/Th-17 pathway genes, IL12B encoding the heterodimeric subunit of IL-23 and IL23R encoding the IL23 receptor, were identified as leprosy susceptibility genes in different populations." (PMID 32373110, 2020). "Thus, the leprosy susceptibility loci, including NOD2, RIPK2, TNFSF15, LACC1, LRRK2, IL12B, and HLA‐DR in phagocytes and IL23R, TYK2, and CSK in T cells, may interfere with the synergistic antimicrobial response between phagocytes and T cells." (PMID 38020709, 2023). "We also validated two previously identified risk factors for leprosy: the missense variant rs3764147 in the LACC1 gene (OR = 1.52 [1.41–1.63], combined p-value = 5.06x10-14), and the intergenic variant rs6871626 located close to the IL12B gene (OR = 0.73 [0.61–0.84], combined p-value = 6.44x10-8)." (PMID 32421744, 2020). "RR specimens also expressed S100A12, which encodes an antimicrobial protein induced by TLR2/1L and IFN-γ in human macrophages, as well as IL12B and IL12RB2, known to be involved in host defense against leprosy." (PMID 40569678, 2025). "Patients co-infected with leprosy and SARS-CoV-2 have elevated levels of IL-6 and IL-12B and develop neuropathy." (PMID 36157452, 2022).
breast carcinoma (9 papers, 2015 to 2025). "We have identified four mouse myeloid subpopulations that highly correlate with breast cancer metastasis to lung, including Tppp3+ monocytes, Isg15+ macrophages, Ifit3+ neutrophils, and Il12b+ DCs." (PMID 37483625, 2023). "A more detailed analysis of 1100 patients with breast cancer (BRCA) revealed significant positive correlations between Il12b, Ifng, Ccl4, Ccl5, Cxcl9, and Cxcl10 gene expression levels and tumor infiltration of CD8+ T cells and M1 macrophages." (PMID 34446712, 2021). "Obviously, proportions of ISG15+ macrophages and IFIT3+ neutrophils in primary tumor have low levels as that in normal lung but not TPPP3+ monocytes and IL12B+ DCs, which indicate that these myeloid subpopulations may have different degrees of association with breast cancer metastasis to lung." (PMID 37483625, 2023). "A nomogram was constructed using 7 IRGs, including GPR132, IFITM1, IL12B, IL18, IRF7, KCNMB2, and TACR1, to predict the 1-, 2-, and 3-year survival of breast cancer patients." (PMID 37304237, 2023). "Except for CCL19, RAET1G, IL12B, CXCL13, CCL22, and NOS1 were significantly highly expressed in breast cancer at the mRNA level." (PMID 36292723, 2022). "Association with TGFBR2 rs1367610 but not IL12B variants replicated using BCAC Asian samples and the independent Prospective Study of Outcomes in Sporadic versus Hereditary Breast Cancer Study and yielded a combined HR of 1.57 ((95% CI 1.28 to 1.94), P = 2.05 × 10−5) without study heterogeneity." (PMID 25849327, 2015).
ulcerative colitis (9 papers, 2009 to 2023). An inflammatory bowel disease involving the mucosal surface of the large intestine and rectum. "In a previous genome-wide meta-analysis study of ulcerative colitis, the most likely candidate gene assigned to this SNP by Gene Relationship Across Implicated Loci (GRAIL) pathway analysis was IL12B." (PMID 32421744, 2020).
autoimmune disease (8 papers, 2012 to 2025). A disorder resulting from loss of function or tissue destruction of an organ or multiple organs, arising from humoral or cellular immune responses of the individual to their own tissue constituents. "Eight SNPs of the three genes (IL-12B, IL-12Rβ1 and IL-12Rβ2) were selected for our study, whereby the choice was dictated by previous studies showing a definite association with other autoimmune diseases." (PMID 24859272, 2014). "Indeed, IL-12b has been found to associate with several autoimmune diseases including psoriasis, rheumatoid arthritis, and type 1 diabetes." (PMID 22666261, 2012). "The association of IL-12b with several autoimmune diseases has been well revealed." (PMID 22666261, 2012). "One drug targeting IL12B named Ustekinumab has been approved to treat autoimmune diseases including IBD." (PMID 36857861, 2023). "Newly identified PBC risk loci overlap with those of other autoimmune disorders and harbour several immunologically relevant candidate genes, most notably chemokine ligand 20 (CCL20) and interleukin 12B (IL12B)." (PMID 26394269, 2015). "This also implies that, at least in Chinese mainland population, rs6887695 in IL-12b gene may not only be a risk factor specific to SLE, but also might be a contributor to the severity of this autoimmune disease." (PMID 22666261, 2012). "Owing to the important role of IL-12 and IL-23 during the immune response, IL-12b, the common component of IL-12 and IL-23, might be a candidate gene of autoimmune disease." (PMID 22666261, 2012). "Exploring the association of IL-12b with disease risk of SLE in our and others' work could provide us with a common genetic background for autoimmune disease." (PMID 22666261, 2012).
cerebral malaria (7 papers, 2008 to 2018). A sequestration of Plasmodium falciparum in the brain, which can cause coma and/or seizures. "A mutation in the promoter region of IL12B, IL12B-pro (rs17860508) has been associated with susceptibility to cerebral malaria." (PMID 23316245, 2012). "This is supported by the fact that different malaria phenotypes such as hyperparasitemia, severe malarial anemia or cerebral malaria are often found to be associated with IL12B gene while the genetic alliance between parasitemia with LTA is seldom unequivocal." (PMID 23071570, 2012). "A functional promoter variant in IL12B, IL12Bpro (rs17860508) is associated with protection against cerebral malaria in children." (PMID 20350312, 2010). "A significant association of the IL12B promoter CTCTAA allele with cerebral malaria was replicated in a Thai population." (PMID 20003322, 2009). "An IL12B promoter allele, CTCTAA, at rs17860508 has been reported to be associated with susceptibility to cerebral malaria in African populations." (PMID 20003322, 2009). "The purpose of this study is to assess whether the IL12B promoter allele, CTCTAA, is associated with susceptibility to cerebral malaria in Thais." (PMID 20003322, 2009).
rheumatoid arthritis (7 papers, 2008 to 2026). A chronic, systemic autoimmune disorder characterized by inflammation in the synovial membranes and articular surfaces. "Gene polymorphisms in cytokines IL-17F (7488 A/G) and IL-12B (1188 A/C) can predict disease susceptibility and severity in Bangladeshi rheumatoid arthritis patients." (PMID 38344692, 2024). "Disease activity and severity measures of rheumatoid arthritis were substantially (P < 0.05) higher in the IL-17F (7488 A/G) GG genotype than in the AA genotype and in the IL-12B (1188 A/C) AC and CC genotypes than in the AA genotype." (PMID 38344692, 2024). "We aimed to investigate the expression of pro-inflammatory cytokine genes TNFA, IL6, IL12B, IL23, IL18 and immunoregulatory genes FOXP3, TGFB1, and IL10 in the peripheral blood of patients with rheumatoid arthritis (RA) at messenger ribonucleic acid (mRNA) level." (PMID 38534783, 2024).
ankylosing spondylitis (6 papers, 2010 to 2018). An autoimmune chronic inflammatory disorder characterized by inflammation in the vertebral joints of the spine and sacroiliac joints. "This study aims to determine whether the genetic polymorphisms of IL-12B gene is a susceptibility factor to Ankylosing spondylitis (AS) in mainland Han Chinese population." (PMID 26103568, 2015). "As the genes IL23R, STAT3, and IL12B all influence Th17 lymphocyte differentiation/activation, this provides further evidence implicating the Th17 lymphocyte subset in the pathogenesis of ankylosing spondylitis." (PMID 21152001, 2010).